LINC02347 (long independently transcribed non-coding RNA 2347)
Gene: Long non-coding RNA gene on chromosome 12 (126,438,837 to 126,472,790, forward strand). Ensembl gene ENSG00000214043.
Diseases named in the same sentence as LINC02347 in open-access papers:
LINC02347 is named in the same sentence as 1 disease in open-access papers, as found by Europe PMC text mining. Sharing a sentence is not in itself a finding about the gene and the disease. The quoted sentences say what the papers report.
depression (1 paper, 2019). "LncRNA LINC02347 on 12q24.32 was uniquely associated with alcohol-induced depression in EA." (PMID 30718457, 2019).